EGFR (epidermal growth factor receptor)
Diseases named in the same sentence as EGFR in open-access papers (continued):
Sharing a sentence is not in itself a finding about the gene and the disease.
tumor (continued). "Through comparative analysis with published smoking-related LUAD, we postulate that the high intra-tumor heterogeneity observed in Asian EGFR-mutant LUAD may be contributed by an early dominant driver, genomic instability, and low background mutation rates." (PMID 29335443, 2018). "Epidermal growth factor receptor (EGFR) is a crucial regulator in tumor growth." (PMID 30223861, 2018). "Thirty-seven patients had tumor sample available for EGFR amplification analysis by FISH." (PMID 29352306, 2018). "Total EGFR was detected with higher relative intensity in IC tumor vs. normal brain tissue." (PMID 30464169, 2018). "Interestingly, at cut-off values >5% of the tumour cells with positive staining, the co-expression of EGFR/HER-2, EGFR/HER-3, EGFR/c-MET, and EGFR/HER-2/HER-3 were all associated with a poorer disease free-survival in the univariate analysis." (PMID 29731973, 2018). "In summary, there is not sufficient evidence to demonstrate that the EGFR mutation resulted in crizotinib resistance in this case because of radiological shrinkage of original tumour lesions and pathological features of new-onset lesion biopsy." (PMID 30029601, 2018). "Among tumor-associated immune cells, tumor-associated macrophages were found to promote CSC-like phenotypes through Milk Fat Globule-EGF Factor 8 (MGF-E8)/STAT3 and Sonic Hedgehog pathways, or through EGFR/STAT3/Sox2." (PMID 29588647, 2018). "Whilst reduced tumor perfusion/permeability measured by DCE-MRI may thus be indicative of resistance to EGFR antagonists, it also reflects diminished drug delivery and hence response." (PMID 30083516, 2018). "Moreover, immunohistochemistry of human CCA samples revealed positivity for HB-EGF in myofibroblasts and tumor cells, while EGFR was present in CCA cells." (PMID 30249019, 2018). "EGFR was highly expressed in various types of tumor tissues, and the overexpression of EGFR could be detected in more than 90% of HNSCC cases." (PMID 30519541, 2018). "Specifically, in EGFR positive lung cancer patients treated with tyrosine kinase inhibitors (TKI) ctDNA has shown reliable correlations with tumor load and changes in response to treatment, indicating a potential utility of this approach in the clinical management of NSCLC." (PMID 29416630, 2018). "We show similar levels of EGFR expression in growing keratinocytes and tumor cells." (PMID 29989001, 2018). "In contrast, in an oncogene-driven never-smoker LUAD, a dominant driver e.g., EGFR mutation, in the context of low-mutation rates—is sufficient to allow expansion of early tumor cells with few co-drivers." (PMID 29335443, 2018). "Furthermore, in vivo studies showed that SCIN deletion slowed tumour growth and decreased EGFR expression." (PMID 29744289, 2018). "When tumor tissue is not accessible, plasma cfDNA provides a promising diagnostic approach for detecting EGFR mutations and has been shown to be effective for diagnosis in meta-analysis." (PMID 30526536, 2018). "At 7p11.2, the intergenic variant rs75061358, which is located in the genomic vicinity of EGFR, was associated with EGFR amplified tumours and not those without amplification." (PMID 29460007, 2018). "This might explain our results for the comparison of EGFR expression in primary tumour vs. normal mucosa." (PMID 29743718, 2018). "The predefined collection of tumor tissues of patients enrolled in the prospective trial allowed a successive investigation of the role of EGFR mutational status, both in ECD and TKD, and the EGFR amplification." (PMID 29352306, 2018). "Osimertinib, a third-generation EGFR-TKI, that targets activating mutations (EGFRm) and resistance mutations (T790M), has demonstrated robust systemic activity and a better CNS penetration with sustained tumor regression of BM." (PMID 29881714, 2018).
tumor (continued). "Although cetuximab alone did not cause DDR, PC3 tumours displayed enhanced cell death, presumably due to the competent binding affinity of cetuximab to EGFR, a property that minimizes cancer cell survival." (PMID 30333494, 2018). "Similarly, a caninized full Ab against epidermal growth factor receptor (EGFR) induces significant inhibition in proliferation in vitro and viability reduction in canine tumor cells that overexpress EGFR." (PMID 30101148, 2018). "EGFR blocking also induced shifts of Epi-CSCs into the differentiating cell compartment which typically has greater sensitivity to chemo/radiation, an effect expected to enhance the overall response of tumour cell populations to adjunctive therapies." (PMID 29568372, 2018). "Inhibition of HER2 may play a potential role in antiproliferation of tumor, and inhibition of EGFR and combination therapy with TKIs could be useful in EGFR- or HER2-overexpressing ESCC." (PMID 30373221, 2018). "Epidermal growth factor receptor (EGFR) mutations enable constitutive active downstream signaling of PI3K/AKT, KRAS/ERK and JAK/STAT pathways, and promote tumor progression by inducing uncontrolled proliferation, evasion of apoptosis and migration of non-small cell lung cancer (NSCLC)." (PMID 29455644, 2018). "But from day 24 to day 32, knockdown of EGFR indeed reduced GBM tumor growth in vivo." (PMID 30016965, 2018). "It inhibits the autophosphorylation of EGFR, blocking downstream signaling transduction pathways, and inhibits signal transmission of cell mitosis, which is activated by growth factor and prevents tumor cell proliferation." (PMID 29652919, 2018). "In 30% of these, mutations were found at a low allele frequency in pre-treatment tumor tissue, suggesting that newly detected RAS mutation in plasma from patients refractory to anti-EGFR treatment may derive from rare, pre-existing clones in primary tumors." (PMID 30477151, 2018). "A very important property of EGFRvIII-expressing tumor cells consists of their capacity to exert paracrine effects on neighbor cells through the release of microvesicles containing the mutant EGFR or mitogenic cytokines, such as interleukin-6 (IL-6) and leukemia inhibitory factor (LIF)." (PMID 30279357, 2018). "Since PLD2 has been reported to promote the EGF receptor (EGFR) endocytosis through the activation of the Dynamin GTPase39, PLD2 might inhibit the EGF/EGFR circuit among tumor cells and stromal cells by limiting cell surface EGFR of stromal cells." (PMID 29674728, 2018). "To determine whether SEMA3C can drive activation of EGFR and MET signaling in other cell types, we first screened cBioPortal for Cancer Genomics data for tumor types that showed an association of high SEMA3C expression and poor prognosis." (PMID 29348142, 2018). "EGFR is an important target for mediating tumor metastasis and adhesion." (PMID 30547012, 2018). "The number of reads for EGFR exons corresponding to the patient’s tumour is given in red type." (PMID 30305059, 2018). "Considering that EGFR is a widespread tumor marker also expressed on normal epithelial cells, the UniCAR technology might be an appropriate solution for efficient EGFR-targeted therapy that simultaneously provides the necessary control mechanisms." (PMID 29876011, 2018). "Moreover, HIF-2α (but not HIF-1α) has been shown to cooperate with a number of oncoproteins frequently deregulated in cancer, such as c-Myc, epidermal growth factor receptor, and K-Ras and promoted tumor aggressiveness, EMT and invasion." (PMID 29481555, 2018). "Another interesting point is that EGFR has been shown to be unstable during tumor progression." (PMID 30411543, 2018). "EGFR cooperates with impaired Hippo pathway signalling, leading to tissue overgrowth and also with the overexpression of the bantam micro-RNA (which is a downstream target of Yki and also of EGFR signalling), leading to overgrown invasive tumours." (PMID 29693007, 2018).
tumor (continued). "Further, GBM is remarkably dependent on cholesterol for survival, rendering these tumors sensitive to LXR agonist-dependent cell death, based on identifying and targeting tumor co-dependencies shaped both by aberrant EGFR-mTOR signaling and the brain’s unique biochemical environment." (PMID 30347859, 2018). "In addition to poor outcome, patients with EGFR alterations tend to be hyperprogressors with significantly increased tumor growth rate after receiving PD-1/PD-L1 inhibitors." (PMID 30294272, 2018). "Key oncogenic kinase drug targets include the PIK3CA, BRAF, and epidermal growth factor receptor (EGFR), which activates significant tumor cell signaling pathways and is related to the mutations and/or deletions in phosphatase and tensin homolog (PTEN), a phosphatase that negatively regulates PI3K." (PMID 29455673, 2018). "This may in part explain differential responses of tumors, e.g. with respect to local tumor control, after combined radiotherapy and RTKi vs. anti-EGFR." (PMID 30042828, 2018). "Hence, the biological impact of E-cadherin/EGFR complex at the junctions in relation with PLEKHA7 await further investigations in tumor cells others than EOCs." (PMID 29996940, 2018). "The results showed higher CDR1-AS (and lower hsa-miR-7) expression in EGFR-high expressing tumours." (PMID 29941867, 2018). "Cetuximab blockade of EGFR will inhibit tumor growth, DNA damage repair, and metastasis." (PMID 30192802, 2018). "Following our observation of an EGFR mutation, a complementary immunohistochemical study was performed in order to rule out a diagnosis of bronchopulmonary carcinoma: the tumor cells did not expresss polyclonal AE1/AE3 cytokeratin, CK7, NapsinA, TTF1 or P40." (PMID 30305059, 2018). "EGFR CISH staining revealed >20 copies of the gene per tumor cell." (PMID 29416795, 2018). "EGFR is over-expressed on cSCC cells, particularly in advanced or metastatic tumor tissue." (PMID 29463844, 2018). "Only specific mutations in EGFR respond to treatment, and this response seems independent of the type of tumor." (PMID 30518123, 2018). "Indeed, this tyrosine residue in GPRC5A has been shown to be phosphorylated by RTKs including EGFR to suppress its tumor suppressor function." (PMID 29946230, 2018). "For instance, work in a spontaneous mammary tumor model showed that IL-4/IL-13-activated TAMs, when exposed to tumor-derived colony-stimulating factor-1 (CSF-1), produce epidermal growth factor (EGF), which in turn promotes motility and intravasation of EGF receptor (EGFR)-expressing tumor cells." (PMID 30355585, 2018). "Sex, smoking history, stage, tumor size, EGFR mutations and whole brain radiotherapy had no statistical influence on survival." (PMID 29447182, 2018). "Given the fact that EGFR was a key regulator of tumor metastasis, we sought to elucidate whether miR-548k promoting lymphatic metastasis was through mediating the EGFR signaling pathways." (PMID 30131072, 2018). "AG-1478 increases mAb 806 binding to EGFR and induces the formation of inactive EGFR dimers that can sequester its ligand, while the interaction between AG-1478 and mAb 806 generates additive effect in tumour treatment." (PMID 30333494, 2018). "However, the shielded and EGFR-retargeted virus showed a tumor-to-liver ratio of about 3, constituting an increase by a factor of more than 2500." (PMID 29386504, 2018). "Moreover, we determined that genetic or pharmacological inhibition of EHMT2 expression enhanced TKI sensitivity and suppressed migration and tumor sphere formation in EGFR-TKI-resistant NSCLC cells." (PMID 29374157, 2018). "All patients with a (K)RAS-wild-type tumor had received anti-EGFR monoclonal antibodies." (PMID 29204933, 2018). "EGFR over-expression was observed in multiple malignant tumours originating from epithelial cells." (PMID 30001205, 2018).
tumor (continued). "Based on these data, promoter DNA methylation may be the main regulatory mechanism of AREG/EREG expression, which may explain, at least in part, the association between right-sided tumor location, CIMP-status and anti-EGFR treatment response in mCRC." (PMID 34532592, 2018). "Interestingly, the KRAS mutant alleles, which emerge at the time of disease progression, decline at the suspension of anti-EGFR therapy, thus indicating the dynamic mode of the tumor cell population that was confirmed in experimental models." (PMID 29534749, 2018). "However, the T790M mutation itself does not interfere with ATP-binding and activation of EGFR, thus the tumor remains dependent on the EGFR pathway." (PMID 29632655, 2018). "Recent data from tumour sequencing suggested EGFR may be subclonal in a small subset of EGFR‐mutant NSCLC tumour, which agrees with our hypothesis." (PMID 29848757, 2018). "EGFR signaling follows three general steps: a ligand-monomeric EGFR interaction, dimerization (either homodimer or heterodimer) coupled with autophosphorylation through tyrosine kinase activity, and signal transduction for tumor-related properties." (PMID 29455655, 2018). "EGFR overexpression results in aggressive tumor behavior, radiation resistance, and poor prognosis." (PMID 30227608, 2018). "Then, we sought to determine whether miR-874 inhibits tumor growth through the DOR/EGFR/ERK pathway." (PMID 29374140, 2018). "EGFR activates beta-catenin through PI3K/Akt in tumor cells." (PMID 30202417, 2018). "Smo crosstalk with EGFR-mediated signaling has been highlighted in several tumours, but how EGFR and Shh signaling crosstalk to promote NSC differentiation towards the OPC lineage remains unclear." (PMID 30463396, 2018). "In another study, the same authors 28 verified that both the PAFR and EGFR signaling pathways promote tumor cell survival and migration in this tumor type and that the combined targeting of both receptors significantly reduced tumor growth and progression in nude mice." (PMID 30328954, 2018). "Indeed, between the paired primary tumor and tumor-derived DNA in CSF, 75% of samples had a concordant EGFR status." (PMID 29881714, 2018). "We show that blocking EGFR with cetuximab inhibits the activation of several pathways downstream of EGFR and results in an increased production of inflammatory chemokines and attraction of T cells when the tumor cells are stimulated with IFNγ and TNFα." (PMID 30192802, 2018). "To demonstrate the specificity of the β-catenin inhibitor ICG-001, we have validated β-catenin transcriptional targets that were identified in this study, using HCC827 xenograft tumor samples that were treated with control, EGFR TKI alone or in combination with ICG-001." (PMID 30097569, 2018). "The origin of the study of the EGFR signaling pathway was in tumor pathology." (PMID 30670929, 2018). "EGFR correlation with IL-4 signaling axis genes and correlation between IL-4 tumor and normal." (PMID 29621254, 2018). "In contrast, two treatment-naïve cases with EGFR driver amplicons had high PD-L1 tumor staining." (PMID 29996881, 2018). "Our research provides a proof-of-principle that targeting the alternatively amplified and mutated EGFR by Lycorine could be used to substitute existing EGFR inhibitors and hinder GBM tumor growth." (PMID 30016965, 2018). "LSD1-s111p was enriched in chemoresistant mesenchymal tumour cells after cytotoxic monotherapy, where it may play a role in chemotherapeutic resistance as suggested by our data demonstrating an increase in EGFR, ALDH1A and ABCB5 in these cells." (PMID 29311580, 2018). "Subgroup analysis according to country, tumor stage, histology, line of treatment, EGFR mutation, and study design did not change the results." (PMID 30068310, 2018).
tumor (continued). "It remains unclear how these mechanisms would affect GGA-mediated EGFR transport and tumor growth in vivo." (PMID 29358589, 2018). "Over-expression of EGFR correlates with aggressive tumor behavior and decreased life expectancy." (PMID 29954411, 2018). "The fact that sensitive mutations in LUAD appear also sensitive to TKIs in other tumor types indicates that response to EGFR-TKIs is not specific to the type of tumor, but is specific for the mutation present." (PMID 30518123, 2018). "Generally, surface expression of the receptors VEGFR and EGFR on tumor cells and their interaction with the corresponding growth factors induces tumor-promoting proliferation, expansion, and malignant conversion of cancer cells, as well as tumor-promoting angiogenesis." (PMID 30577587, 2018). "For mCRC patients, the presence or absence of tumor Ras mutations directly impacts on use of anti-EGFR therapy." (PMID 30705875, 2018). "The combination of a metastatic tumour environment with a miniaturized healthy organotypic human skin equivalent make this “safficacy” assay an ideal tool for evaluation of the therapeutic index of EGFR inhibitors and other promising oncology candidates." (PMID 30301942, 2018). "Upon intratumoral administration into A431 tumor xenografts, an EGFR-specific retargeting adapter increased the payload delivery (luciferase) in the tumor by 20-fold, compared to HAdV5HVR7 with a free fiber knob, and by 34-fold compared to a blocked fiber knob virus." (PMID 29386504, 2018). "In this case, a decrease in original tumour lesions was observed before the time of lung biopsy, suggesting that the detectable EGFR mutations had not triggered crizotinib resistance in this period." (PMID 30029601, 2018). "Taken together, in all three models, the most efficient growth inhibition of xenografts was achieved with a combination C-KRAS/PIK3CA-esiRNA, indicating that the combined inhibition of two branches of the EGFR-signaling pathway is very effective in slowing down tumor growth." (PMID 30001368, 2018). "KRAS genotyping in tumor samples is a decisive clinical test for the anti-EGFR therapy management." (PMID 30406144, 2018). "Plasma circulating tumour DNA (ctDNA) is a non‐invasive method that has been used to identify EGFR mutations and other genetic drivers in NSCLC and in response to treatment of NSCLC patients with EGFR‐TKIs." (PMID 29848757, 2018). "The C225-conjugated micelles may interact with EGFR, which would not only enhance the internalization and accumulation of the photosensitizer in cancer cells, but also directly inhibit tumor growth." (PMID 29470420, 2018). "In CTG1014, which carries EGFR L858R/T790M mutations, a single dose of 3.0 mg/ml RN765C was sufficient to induce tumor regression with similar efficacy as two doses of paclitaxel and was more efficacious than multiple doses of gemcitabine, carboplatin or cetuximab." (PMID 30323890, 2018). "While the identification of robust biomarkers capable of identifying tumor subsets that may benefit from wt EGFR targeting is a major challenge ahead, the present work provides a mechanism‐based rationale for future clinical and translational research." (PMID 30021798, 2018). "To evaluate the use of Bamgineer for circulating tumor DNA analysis, we simulated the presence of an EGFR gene amplification in read alignments from a targeted 5-gene panel (18 kb) applied to a cell-free DNA from a healthy donor and sequenced to >50,000X coverage." (PMID 29590101, 2018). "However, tumours have redundant signaling pathways for tumour progression and often develop resistance to single EGFR inhibitors." (PMID 29115879, 2018). "Several mechanisms may be related to primary resistance to EGFR-TKIs, such as low EGFR gene copy number and intra-tumor genetic heterogenicity." (PMID 30055587, 2018).